ESYT2 (extended synaptotagmin 2)
Description:
Tethers the endoplasmic reticulum to the cell membrane and promotes the formation of appositions between the endoplasmic reticulum and the cell membrane. Binds glycerophospholipids in a barrel-like domain and may play a role in cellular lipid transport. Plays a role in FGF signaling via its role in the rapid internalization of FGFR1 that has been activated by FGF1 binding; this occurs most likely via the AP-2 complex. Promotes the localization of SACM1L at endoplasmic reticulum-plasma membrane contact sites (EPCS).
Synonyms: E-Syt2; FAM62B; KIAA1228; CHR2SYT
Tractability: Small molecule: a structure with a bound ligand is known. Antibody: UniProt places it where antibodies can reach, with high confidence; its Gene Ontology location is reachable by antibodies, with high confidence; UniProt predicts a signal peptide or a membrane-spanning region. PROTAC: ubiquitination databases record sites on it; its protein half-life has been measured.
Gene: Protein-coding gene on chromosome 7 (158,730,995 to 158,830,253, reverse strand). Ensembl gene ENSG00000117868.
Subcellular location: Cell membrane; Endoplasmic reticulum membrane
Subcellular location (Human Protein Atlas): Cytosol; Plasma membrane
Pathways (Reactome):
Transport of small molecules: Glycosphingolipid transport
Gene Ontology:
Molecular function: cadherin binding; calcium ion binding; calcium-dependent phospholipid binding; identical protein binding; phosphatidylcholine binding; phosphatidylethanolamine binding; phosphatidylinositol binding; protein binding; lipid binding
Biological process: lipid transport
Cellular component: cytoplasmic side of plasma membrane; endoplasmic reticulum membrane; endoplasmic reticulum-plasma membrane contact site; membrane; organelle membrane contact site; plasma membrane
Genetic constraint (gnomAD): Loss-of-function variants: 53 observed, 97.36 expected, observed/expected ratio (o/e) 0.54, 90% interval 0.44 to 0.68. The upper end of that interval is the gene's LOEUF score, 0.68, which puts it in group 2 of 6, group 1 being the genes least tolerant of losing a copy. Missense variants: 995 observed, 1,043.2 expected, observed/expected ratio (o/e) 0.95, 90% interval 0.9 to 1. Synonymous variants: 480 observed, 415.94 expected, observed/expected ratio (o/e) 1.15, 90% interval 1.07 to 1.24.
Homologues: Orthologues: macaque ESYT2 (96% identical), chimpanzee ESYT2 (95% identical), rabbit ESYT2 (92% identical), rat Esyt2 (92% identical), mouse Esyt2 (90% identical), dog ESYT2 (89% identical), pig ESYT2 (87% identical), guinea pig ESYT2 (77% identical), zebrafish esyt2a (58% identical), zebrafish esyt2b (57% identical), tropical clawed frog esyt3 (45% identical), Drosophila melanogaster Esyt2 (32% identical), and 1 more. Paralogues in human: ESYT1 (43% identical), ESYT3 (41% identical).
Diseases named in the same sentence as ESYT2 in open-access papers:
ESYT2 is named in the same sentence as 11 diseases in open-access papers, as found by Europe PMC text mining. Sharing a sentence is not in itself a finding about the gene and the disease. The quoted sentences say what the papers report.
breast carcinoma (3 papers, 2018 to 2024). "While some of the top candidates have been previously reported to play a role in cancer (FLNB, MAP3K7, NFYA, and ESYT2) others were identified to be breast cancer-relevant for the first time (NEDD4L, MARK2, ABI1)." (PMID 38664594, 2024). "We found several targets of QKI and RBFOX1, including FLNB, SLK, USO1, ENAH, ESYT2, NUMB and ARHGEF1, to be among the most differentially spliced genes in basal B breast cancer cell lines." (PMID 30059005, 2018).
lung carcinoma (2 papers, 2015 to 2020). "In lung cancer cells, the short and long variants of ESYT2 were implicated in the cortical distribution of actin and endocytosis, respectively." (PMID 33048956, 2020).
cancer (5 papers, 2021 to 2024). A tumor composed of atypical neoplastic, often pleomorphic cells that invade other tissues. "The membrane transporter ABCC1 (MRP1), which confers multidrug resistance to cancer cells, was also enriched in the Panc-1 library, along with three other SLC transporters, SLC4A2, SLC30A1, and SLC12A7 (KCC4), plus the epidermal growth factor receptor EGFR and lipid transport protein ESYT2." (PMID 37295717, 2023).
tumor (3 papers, 2020 to 2023). "Missense variants were found in MYPN, SERPINB8 (SPB8) and ESYT2, which were among the top ten most upregulated proteins in the tumour group." (PMID 33048956, 2020). "Together, downregulation of QKI-5 expression in NSCLC appears to play a role in tumor invasion and metastasis by dysregulating cytoskeleton remodeling, at least in part through reduced exon skipping in the ESYT2 and ADD3 genes and probably several other genes involved in these processes." (PMID 34065983, 2021).
ESYT2 also shares sentences with these, for which no sentence is quoted: Behcet’s syndrome (1 paper); Dystonia (1); leukemia (1); malignant melanoma (1); neurodevelopmental disorder (1); sarcoidosis (1); triple-negative breast carcinoma (1).